PRR20G (proline rich 20G)
Tractability: No criterion of Open Targets' tractability assessment is met for any kind of drug.
Gene: Protein-coding gene on chromosome 3 (127,283,783 to 127,288,046, reverse strand). Ensembl gene ENSG00000239620.
Homologues: Orthologues: chimpanzee PRR20G (96% identical), macaque PRR20G (75% identical), dog PRR20G (37% identical). Paralogues in human: PRR20A (56% identical), PRR20B (56% identical), PRR20C (56% identical), PRR20D (56% identical), PRR20E (56% identical).